TRADD (TNFRSF1A associated via death domain)
Diseases named in the same sentence as TRADD in open-access papers (continued):
Sharing a sentence is not in itself a finding about the gene and the disease.
tumor (25 papers, 2008 to 2026). "In HCC, TRADD expression is associated with tumor differentiation, promoting tumor growth by activating pro-survival signals." (PMID 40565323, 2025). "TRADD deficiency in mice accelerates tumor formation in a model of chemically induced carcinogenesis." (PMID 37864090, 2023). "The tumor suppressive miR-31 that targets TNF receptor associated death domain (TRADD) and inhibits NF-kappaB activation is deleted in the majority of HGGs and therefore tumor proliferation is increased." (PMID 31142339, 2019). "Consistent with this, TRADD-deficient mice exhibit enhanced tumor formation in DMBA/TPA-induced skin carcinogenesis." (PMID 28611389, 2017). "In conclusion, our findings indicate that CL-387785 induces necroptosis in tumor cells via the TRADD/RIPK1/NF-κB/CD80 signaling pathway, thereby sensitizing tumors to anti-PD-1 therapy." (PMID 41694588, 2026). "Small-molecule inhibitors such as ICCB-19 and apostatin-1 (Apt-1), which modulate TRADD activity, have demonstrated significant efficacy in inflammatory and tumor models." (PMID 40565323, 2025). "Intriguingly, TRADD expression correlates with TRAIL sensitivity in HepG2 tumor cells, suggesting its potential as a target to overcome TRAIL resistance." (PMID 40565323, 2025). "It has been recently reported that nuclear localization of TRADD promoted p19Arf protein stability and tumor suppression by regulating ULF-dependent p19Arf ubiquitylation in a mouse model of skin cancer." (PMID 28611389, 2017). "We believe miR-31 suppresses tumor formation, in part, by targeting TRADD to reduce NF-κB activation." (PMID 26164206, 2015). "Notably, TRADD expression correlates with tumor differentiation: a study of 39 HCC patients revealed significantly higher TRADD positivity in poorly differentiated HCC (52.4%) compared to moderately/well-differentiated cases (22.2%)." (PMID 40565323, 2025). "Drug distribution, metabolic stability, and tumor microenvironmental factors may influence Mebendazole’s ability to modulate the PELI3/TRADD axis in living systems." (PMID 41584581, 2025). "In addition, CYCS and NFKB1 presented low expression, while IKBKB and TRADD presented high expression in TCGA and clinical tumor samples." (PMID 35502302, 2022). "Recently we identified a novel tumour-suppressive role of TRADD independently of TNFR1 signalling." (PMID 24758719, 2014). "Intranucleus TRADD was found to modulate the interaction between p19 (Arf) and its E3 ubiquitin ligase ULF, thereby promoting p19 (Arf) protein stability and tumour suppression, suggesting that TRADD may play roles in modulating ubiquitinylation." (PMID 24758719, 2014). "In addition, the expression of key genes in the TNF-α/NF-κB signaling, including NFKB1 (p50), RelA (p65), TNFRSF1A (TNFR1), TNFR1-associated death domain protein (TRADD), and TNF receptor-associated factor 2 (TRAF2), was examined in the cell lines and tumor tissues of EBV-associated cancers." (PMID 35008199, 2021). "Detailed mechanistic studies indicated that CL-387785 targets TRADD, recruiting RIPK1 to induce necroptosis in tumor cells, with subsequent nuclear translocation of NF-κB, which regulates CD80 transcription." (PMID 41694588, 2026). "Downregulation of TRADD, CX3CL1, and ILI24 implies dysregulation in TNFR1 signaling, immune recruitment, and tumor suppression." (PMID 38456941, 2024). "This reduction is a consequence of the dynamic shuttling of TRADD from the cytoplasm into the nucleus, which regulates the interaction between P19 (ARF) and its E3 ubiquitin ligases, thereby inhibiting tumor growth." (PMID 37864090, 2023). "Collectively, our findings indicate that STOML2 facilitates the recruitment of TRADD and sustains NF-κB activity to upregulate CCND1, VEGFC and PD-L1, which consequently leads to tumor proliferation, angiogenesis, immune escape and poorer clinical outcomes in human in CRC." (PMID 38214751, 2024).
tumor (continued). "IHC staining analysis suggested that TRADD, VDAC3, JMJD7-PLA2G4B, and TRAF2 expression levels were upregulated in COAD tumor tissues compared with those in normal gastric tissues at the protein level, which was consistent with the expression pattern of the genes." (PMID 36505813, 2022). "Chio and colleagues suggested that TRADD shuttles dynamically from the cytoplasm into the nucleus to modulate the interaction between p19Arf and its E3 ubiquitin ligase ULF, thereby promoting p19Arf protein stability and thus tumor suppression." (PMID 28611389, 2017). "NFKB is activated TRADD-, TRAF3- and FADD-dependently and also plays a key role in the survival of tumor cells by inducing expression of anti-apoptotic genes such as Bcl2, Bcl2l1, vascular endothelial growth factor (VEGF), and X-linked inhibitor of apoptosis (XIAP)." (PMID 19077262, 2008).
cancer (15 papers, 2009 to 2025). A tumor composed of atypical neoplastic, often pleomorphic cells that invade other tissues. "While direct studies on the downregulation of TRADD in carcinogenesis may be limited, alterations in TNFR1 signaling pathways, including TRADD, have been implicated in various malignant neoplasms." (PMID 38456941, 2024). "Some studies suggest that dysregulation of TNFR1 signaling, which includes TRADD, can contribute to cancer development and progression." (PMID 38456941, 2024). "In the collected clinical specimens, qPCR results revealed notably lower CYCS and NFKB1 expression and notably higher IKBKB and TRADD expression in cancer tissues than in healthy paracarcinoma ones (P < 0.05)." (PMID 35502302, 2022). "Our data suggest that TRADD is a potential target for initiating cancer cell death in response to therapeutic DNA-damaging agents." (PMID 28611389, 2017). "Of these genes, TNFRSF1A and TRADD were found to be upregulated since they work as the trigger molecules of the apoptotic cascade in cancer cells whereas antiapoptotic genes MCL-1 and LTBR were found to be downregulated." (PMID 20673323, 2010). "Given our data, TRADD might be a potential drug target to promote cancer cell death in response to chemotherapeutic DNA-damaging agents." (PMID 28611389, 2017). "Taken together, our data suggest that TRADD could be a potential target for DNA damage-based chemotherapeutic agent-induced cancer cell death." (PMID 28611389, 2017). "This is an important cytokine that plays a role in cancer, with two protein families implicated in the signaling mediated by the TNF receptor: 1) death-domain proteins, such as TRADD, FADD, TNFR1, RIP; and 2) TRAF domain-containing proteins, such as TNFR2, CD40, TRAF1, TRAF6." (PMID 26143641, 2015). "Therefore, TRADD may have dual pro-cancer and anti-cancer functions, depending on cellular localization." (PMID 28611389, 2017). "Our analysis showed that AATF, LGALS3, and SRC are up regulated in 8/13 of cancer models, and CDC2L2, E2F6, LGALS9, PDCD8, RELB, TRADD, and TRAF2 in 7/13." (PMID 19402918, 2009). "On one hand, TNF-α promotes cancer cells survival by activating TNFRs, vascular cell adhesion molecule 1 (VCAM1) and altering the protein complex I and II (complex I consists of TRADD, TRAF2 and RIP and Complex II that consists of TRADD, RIP, FADD and caspase-8)." (PMID 35954156, 2022). "The protein levels of TRAF2 and TRAF6 were reduced in cancer cell lines treated with NA, but not TRAF3, TRADD, and FADD." (PMID 25575821, 2015).
infection (7 papers, 2012 to 2025). The state of being infected such as from the introduction of a foreign agent such as serum, vaccine, antigenic substance or organism. "During early infection (4 hpi), TRADD suppresses apoptosis by downregulating RIP1, thereby favoring parasite survival." (PMID 41463813, 2025). "The enteropathogenic and enterohemorrhagic Escherichia coli T3SS effector NleB inhibits death domain-containing proteins, including FADD and TRADD, leading to reduced NF-κB pathway activation and impaired caspase-8-dependent host cell death during infection." (PMID 28069818, 2017). "More importantly, the TRADD–/– mice infection model confirmed this result." (PMID 32766249, 2020). "TRADD–/– mice infection model confirmed this result, which might be correlated with its role of dynamic equilibrium in both cell death and NF-κB signaling." (PMID 32766249, 2020). "Our findings thus suggest that TRADD might promote the apoptosis of intestinal cells, along with having an adverse effect on host defense against infection by C. perfringens type C." (PMID 32855971, 2020). "Therefore, FADD and TRADD are likely to represent genuine targets of SseK proteins during host cell infection." (PMID 28069818, 2017). "Conversely, the late phase of infection is executed via the convergence of the mitochondrial pathway (driven by Bax activation and MOMP), the death receptor pathway (via FasL and TRADD/FADD signaling), and the amplification of stress signals from the ER." (PMID 41463813, 2025). "Conversely, the late phase of infection is characterized by the convergence of the mitochondrial pathway (driven by Bax activation and MOMP), the death receptor pathway (via FasL and TRADD/FADD signaling), and the amplification of ER stress signals." (PMID 41463813, 2025). "Further investigations revealed that TRADD and FADD exhibit opposing functions at different stages of infection." (PMID 41463813, 2025). "The opposing roles of TRADD and FADD at different infection stages reveal a sophisticated spatiotemporal regulatory strategy employed by Eimeria." (PMID 41463813, 2025). "Furthermore, mouse infection studies showed that SseK1 but not SseK3 rescued the bacterial colonization deficiency contributed by the deletion of NleBc (Citrobacter NleB), indicating that TRADD was the in vivo substrate." (PMID 32766249, 2020). "Although modification of TRADD, FADD, and RIPK1 in in vitro reconstitution system and ex vivo epithelial cell infection system has been studied, the in vivo substrate preference of NleB remains elusive." (PMID 32766249, 2020). "Considering that NleB could modify the DDs of TRADD, FADD, and RIPK1 in cell culture infection system, it is necessary to determine the target in vivo." (PMID 32766249, 2020). "We hypothesized that if NleB interfered with TRADD-mediated signaling during infection, then C. rodentium ΔnleB mutant bacteria would no longer be attenuated in mice with defects in TRADD." (PMID 32766249, 2020). "SseK1 and SseK3 from S. Typhimurium SL1344 specifically modified TRADD DD and TNFR1 DD, respectively, while SseK2 exhibited no obvious arginine GlcNAcylation activity toward DD proteins during infection." (PMID 32766249, 2020). "Further, the upregulation of TRADD and MLKL alongside the downregulation of the necroptosis inhibitor STUB1 suggests the priming, but not complete activation, of necroptosis in our in vitro infection model." (PMID 37795301, 2023). "Infection-induced arginine-GlcNAcylation of FADD and TRADD (but not of the GFP control) was dependent on the SseK proteins: SseK1 modified FADD while both SseK1 and SseK3 induced modification of TRADD." (PMID 28069818, 2017).
bacterial infections (1 paper, 2025). "Whereas Class2 uniquely included pathways related to bacterial infections (e.g., E. coli, Salmonella) together with actin-cytoskeleton and T-cell modules (e.g., ACTB, PFN1, RAC2, PIK3CD, CD3D/CD3G, STING1, TRADD, CASP8, BCL2, HLA-F)." (PMID 41394852, 2025).
TRADD also shares sentences with these, for which no sentence is quoted: lung carcinoma (3 papers); hepatocellular carcinoma (2); myeloma (2); acute pancreatitis (1); brain diseases (1); cystic fibrosis (1); dementia (1); dermatitis (1); diffuse large B-cell lymphoma (1); epilepsy (1); glioma (1); inflammation (1); leukemia (1); Lymphadenopathy (1); lymphopenia (1); non-small cell lung carcinoma (1); oral cancer (1); osteoarthritis (1); osteosarcoma (1); ovarian carcinoma (1); Parkinson disease (1); psoriasis (1); rectal cancer (1); rheumatoid arthritis (1); squamous cell carcinoma (1); T cell deficiency (1); T-LGL leukemia (1); Uterine leiomyoma (1).